NLRP3 (NLR family pyrin domain containing 3)
Diseases named in the same sentence as NLRP3 in open-access papers (continued):
Sharing a sentence is not in itself a finding about the gene and the disease.
Obesity (continued). "In the present study, the increase of NLRP3 inflammasome during adolescence was accompanied by cardiomyocyte hypertrophy in DIO rats, which indicated the importance of the NLRP3 inflammasome in the pathogenesis of obesity-realted cardiovascular diseases." (PMID 27686325, 2016). "As such, it is conceivable that obesity-induced activation of NLRP3 promotes activation and infiltration of macrophages into AT leading to increased expression of inflammatory genes." (PMID 27583382, 2016). "For example, it has been shown that the NLRP3 inflammasome is activated by saturated free fatty acids and is involved in obesity-induced inflammation and insulin resistance." (PMID 27229537, 2016). "It should be noted that in these studies, the Nlrp3 inflammasome activity was observed at a relatively late stage of obesity or metabolic stress as the mice were treated with high fat diet for more than twelve weeks." (PMID 27689324, 2016). "Other studies associated NLRP3 inflammasome function with metabolic syndrome and type 2 diabetes, as NLRP3 deficient mice were protected from high fat diet- (HFT-) induced inflammation, glucose intolerance, insulin resistance, and obesity." (PMID 27672241, 2016). "Sphingolipid, ceramide has been reported to initiate Nlrp3 inflammasome formation and activation in different pathological conditions including insulin resistance, obesity, Alzheimer's disease, cystic fibrosis and acute lung injury." (PMID 26980705, 2016). "The present study was designed to investigate the role of acid sphingomyelinase (Asm) gene during obesity and explore its potential effects on Nlrp3 inflammasome activation and consequent glomerular sclerosis/injury." (PMID 26980705, 2016). "Our results, for the first time, demonstrate a novel direct action of endothelial Nlrp3 inflammasome on the development of endothelial dysfunction and injury during the early stage of metabolic disorders such as obesity or high‐fat/cholesterol diet." (PMID 26293846, 2015). "This process of inflammasome activation through NLRP3 is present in many age‐related conditions, such as obesity, and type 2 diabetes." (PMID 26523150, 2015). "Next, we examined the role of Nlrp3 inflammasome in the disassembly of endothelial junction proteins in the coronary endothelium in a HFD‐induced obesity model using Nlrp3+/+ and Nlrp3−/− mice." (PMID 26293846, 2015). "Although obesity induces ER stress, the interplay between hepatic ER stress, NLRP3 inflammasome activation and hepatocyte death signaling has not yet been explored during the etiology of chronic liver diseases." (PMID 26355342, 2015). "Recent studies suggested another possible explanation involving activation of the NLRP3 inflammasome and obesity-induced inflammation." (PMID 25889813, 2015). "In obesity-associated asthma, the development of airway hyperreactivity (AHR) is thought to be dependent on IL-17A and the NLRP3 inflammasome." (PMID 25128964, 2014). "The NLRP3 inflammasome is a multi-molecular complex recently demonstrated as central to obesity-induced IR." (PMID 23675368, 2013). "The pleiotropic effects of inhibition of NLRP3 inflammasome in obesity are evident by improved insulin signaling in adipose tissue, liver, and skeletal muscle and increased insulin secretion in the pancreas." (PMID 23483669, 2013). "Macrophages are recruited to adipose tissue during obesity and represent the largest population of NLRP3 expressing cells in fat." (PMID 23483669, 2013). "It has been shown that activation of caspase-1 and IL-1β processing downstream of NLRP3 lead to inhibition of adipocyte differentiation and contributes to high fat diet-induced obesity." (PMID 24137163, 2013). "Consistent with the causal role of NLRP3 inflammasome activation in the development of inflammation, deletion of Nlrp3 in mice, prevents obesity-induced caspase-1 activation." (PMID 23483669, 2013).
Obesity (continued). "Both NLRP3 and the inflammasome adaptor ASC (apoptotic speck-like protein containing a CARD, known also as Pycard) deficiency ameliorated obesity-induced IR in mice." (PMID 23675368, 2013). "A collection of recent studies have identified the NLRP3 inflammasome as a central sensor that detects obesity-related stress signals and that triggers IL-1β production and subsequent disease pathogenesis." (PMID 23087690, 2012). "Recent studies have identified sensors of “danger signals”, such as the Nlrp3 inflammasome, to contribute to obesity-related inflammation and insulin resistance." (PMID 22848385, 2012). "Collectively these findings have provided us with important insight into the immunological underpinnings of obesity and define pivotal roles for the NLRP3 inflammasome in obesity-induced sterile inflammation." (PMID 23087690, 2012). "All together, these findings render the NLRP3 inflammasome as an attractive pharmacological target against the complications of obesity." (PMID 23316186, 2012). "The identity of the danger signals that activate the NLRP3 inflammasome in obesity remains ill-defined." (PMID 23316186, 2012). "The question why macrophages should be activated in the apparent absence of autoimmune reactions was recently answered by the identification of the NLRP3 inflammasome as an instigator of obesity-induced inflammation and IR." (PMID 23028961, 2012). "Additionally, NLRP3 activation in macrophages can be driven by obesity-related stimuli such as elevated ceramide levels, mitochondrial dysfunction, reactive oxygen species (ROS), and extracellular ATP." (PMID 41596350, 2026). "Thus, the activation of the NLRP3 inflammasome represents a key mechanistic link between obesity and neuroinflammation in MS, mediating inflammatory responses to metabolic disturbances." (PMID 41562846, 2026). "The previously reported abundance of CLS in untreated obesity and their reduction after bariatric surgery suggest that the NLRP3-Caspase-1 axis within CLS may serve as an important mediator of the beneficial metabolic effects associated with bariatric surgery." (PMID 41645554, 2026). "Obesity drives cardiovascular disease primarily through chronic meta-inflammation, yet the precise molecular convergence linking nutrient excess to sustained NLRP3 inflammasome activation in macrophages has remained unclear." (PMID 42112341, 2026). "Background/ Objectives: Obesity is a chronic disease that promotes increased cytokine production mediated by activating a complex of intracellular proteins known as the inflammasome, mainly NLRP3." (PMID 41729927, 2026). "Notably, obesity-induced VAT NLRP3 inflammasome activation is reported to mediate neuroinflammation and subsequent cognitive decline via activation of the microglial interleukin-1 receptor 1 (IL-1R1)." (PMID 40145973, 2026). "The NLRP3 inflammasome is central to obesity-induced inflammation and ED." (PMID 40227195, 2025). "However, our findings also suggest that in people with obesity and COVID-19, the predominant inflammatory pathway activated is the NLRP3 inflammasome, probably leading to pyroptotic cell death mediated by caspase-1." (PMID 40004007, 2025). "Overall, these results suggest that NLRP3−/− mice were less susceptible to the development of HFD‐induced obesity, thus corroborating the relevant role of NLRP3 inflammasome in the pathophysiology of obesity." (PMID 39287080, 2025). "Furthermore, obesity activates NLRP3 inflammasomes, leading to the release of proinflammatory cytokines that further worsen OA symptoms." (PMID 40432960, 2025). "Ceramides, another lipid species elevated in obesity, have also been shown to activate NLRP3." (PMID 40648980, 2025). "In contrast to semaglutide and calorie restriction, only NLRP3 inhibitors significantly lowered cardiovascular inflammatory markers like sVCAM-1 and PCSK9, which indicates potential benefit in cardiovascular risk reduction in individuals with obesity." (PMID 40104296, 2025).
Obesity (continued). "Saturated fatty acids abundant in obesity can potentially trigger NLRP3 inflammasome activation." (PMID 40104296, 2025). "Prior studies have demonstrated that NLRP3 knockout mice are resistant to diet-induced obesity." (PMID 40104296, 2025). "However, upon chronic activation (e.g., in obesity or hypercholesterolemia), NLRP3 became pathologic and promoted disease." (PMID 40095546, 2025). "Our primary goal was to determine whether chronic NLRP3 inflammasome activation in people with obesity is different in critical COVID-19 and in critical chronic conditions." (PMID 40004007, 2025). "Therefore, we analyzed the release of this cytokine in cocultured EGCs (characterized by NLRP3 inflammasome activation ) under mimicking obesity conditions." (PMID 39287080, 2025). "Additionally, it has been demonstrated that NLRP1-derived IL-18 prevents obesity, suggesting that sources other than the NLRP3 inflammasome contribute substantially to IL-18 production." (PMID 39496966, 2025). "Moreover, recent evidence highlights the NLRP3 inflammasome as a key mediator of chronic inflammation in obesity and insulin resistance." (PMID 41301516, 2025). "In order to confirm the interplay among obesity, NLRP3 inflammasome activation and enteric gliosis, we performed a double‐staining immunofluorescence analysis to investigate ASC specks, reflecting an active status of the inflammasome, at level of mucosal and neuromuscular GFAP‐positive glial cells." (PMID 39287080, 2025). "In conclusion, inhibition of the NLRP3 inflammasome–IL-1β pathway in obesity and type 2 diabetes may represent an attractive way to target the pathogenesis of these diseases and their complications." (PMID 39496966, 2025). "A recent follow-up study tested the efficacy of two NLRP3 inhibitors in reversing obesity in mice." (PMID 39496966, 2025). "Targeting NLRP3 vesicles may not only be important for Th2‐high asthma but may also have some positive significance for obesity‐related asthma phenotype." (PMID 39800672, 2025). "Furthermore, in metabolic tissue, NLRP3 activation continues to sustain insulin resistance and cellular dysfunction, thereby accelerating the progression of obesity-related comorbidities." (PMID 41226484, 2025). "Notably, the components of the NLRP3 inflammasome are expressed in adipose tissue, and their expression is upregulated in obesity and insulin resistance." (PMID 40943464, 2025). "The NLRP3 inflammasome acts as a key intracellular sensor of metabolic danger signals, responding to various endogenous and exogenous stimuli that accumulate during obesity and contribute to chronic low-grade inflammation." (PMID 40648980, 2025). "Overall, these findings suggest that moderating obesity-driven inflammatory pathways, particularly IL-6 signaling and NLRP3 inflammasome activation, may reduce clonal expansion and mitigate the metabolic sequelae associated with CHIP." (PMID 41516113, 2025). "NLRP3 inflammasome is a cytosolic multiprotein complex that plays a critical role in innate immunity and regulation of inflammation, particularly in the context of metabolic diseases such as obesity and type 2 diabetes (T2D)." (PMID 40943225, 2025). "It has been demonstrated that combining aerobic and resistance exercise, as well as high-intensity interval training (HIIT), effectively reduces the expression of the NLRP3 gene and the proinflammatory cytokine IL-1β in individuals with obesity and type 2 diabetes." (PMID 40761804, 2025). "The NLRP3 inflammasome has been recognised as a critical sensor of metabolic stress, primarily activated in dysfunctional adipose tissue, and thus significantly contributes to the systemic inflammatory response observed in obesity." (PMID 41226484, 2025).
Obesity (continued). "At the center of this inflammatory process is the NLRP3 inflammasome, an intracellular sensor activated by a wide range of metabolic danger signals that accumulate in obesity, including saturated fatty acids (e.g., palmitate), ceramides, uric acid, high glucose, and islet amyloid polypeptide (IAPP)." (PMID 40943225, 2025). "Recent evidence indicates that diet-induced obesity can predispose to bone non-union by altering neutrophil function; mechanistic studies further implicate activation of the NLRP3 inflammasome as the critical intermediary in this process." (PMID 40727697, 2025). "Obesity and metabolic disorders exacerbate pyroptosis through NLRP3 inflammasome activation." (PMID 40331931, 2025). "Chronic inflammation is a common characteristic of obesity, and inhibiting the NLRP3 inflammasome may help reduce this inflammatory response." (PMID 38732190, 2024). "Pathways identified as important in inflammation, as related to diet and obesity, include the NLRP3 inflammasome, macrophage-mediated chronic low-grade inflammation in adipose tissue, and the toll-like receptor 4 (TLR4) signaling pathway that is activated by saturated fatty acids." (PMID 38978699, 2024). "However, depletion of the NLRP3 inflammasome using knock-out genotyping abrogated the levels of LBP, implicating the NLRP3 inflammasome as a target to mediate obesity-related inflammation." (PMID 38978699, 2024). "Additionally, decreased (P < 0.05) mRNA levels of Nlrp1, Nlrp3 and Nlrp6 in the small intestinal tract obtained from rats with diet-induced obesity were found." (PMID 38315242, 2024). "However, the role of the NLRP3 inflammasome in gut barrier disruption during intestinal inflammation in the context of obesity remains unsettled." (PMID 38315242, 2024). "Mice models with deficient inflammasomes, including NLRP3, apoptosis-associated speck-like protein containing a caspase activation and recruitment domain (ASC), and caspase-1, have exhibited protection against HFD-induced obesity." (PMID 38562155, 2024). "Thus, obesity promotes NLRP3 and macrophage-mediated T-cell activation in adipose tissues, which are also responsible for insulin sensitivity." (PMID 38945951, 2024). "Since this type of macrophage involves the activation of the NLRP3 inflammasome, which is characteristic of the chronic low-grade systemic inflammation present in obesity and insulin resistance, the study of postbiotics as a therapeutic option in obesity deserves further investigation." (PMID 39593945, 2024). "In the present study, IL-18 was the only NLRP3 protein studied which was associated with obesity status, but it was only predictive of SF-12 physical scores at 6-months and RPQ scores at 2-weeks in the severe obesity model." (PMID 38702410, 2024). "Additionally, a cardiac‐specific NLRP3‐deletion mouse model needs to be constructed to investigate the role of cardiomyocyte NLRP3 inflammasome in obesity cardiomyopathy in vivo." (PMID 39604027, 2024). "In the later stages of obesity, failure in NLRP3 inflammasome activation and M1 macrophage regulation is associated with the establishment of ovarian leptin resistance, which is associated with the disruption of ObRb-dependent (canonical) and ObRb-independent (noncanonical) signalling." (PMID 38580672, 2024). "We speculated that NLRP3 inflammasome inhibition ameliorates obesity‐induced cardiac remodeling; however, cardiac aging and sustained HFD for 52 weeks partially reduced its cardioprotective effects." (PMID 39604027, 2024). "Recent studies have shown that SGLT2 inhibitors may inhibit activation of the NLRP3 inflammasome in several animal models, including obesity, lung injury, myocardial infarction, DKD, depression and atherosclerosis." (PMID 39412512, 2024). "In obesity, macrophages and cells of the myeloid lineage are the main cells that express NLRP3." (PMID 39518420, 2024). "Recently, NLRP3-inflammasome has been demonstrated to be a key driver of obesity-induced AF." (PMID 38628316, 2024).
Obesity (continued). "We hypothesized that colchicine could have a great impact on obesity and MS due to its anti-inflammatory effects, especially in the NLRP3 inflammasome, a key component of chronic inflammation in obese patients." (PMID 39590865, 2024). "Other DAMPs involved in TLR-4/9 and canonical NLRP3 inflammasome activation in obesity include elevated palmitate and other saturated fatty acids, glucose, uric acid, C-reactive protein (CRP), ceramide, islet amyloid polypeptide, HMGB1, mitochondrial DNA, and cholesterol crystals/oxLDL." (PMID 39063184, 2024). "In the present work, we hypothesise that temporal fluctuations in ovarian leptin signalling throughout obesity affect the inflammatory response in the organ, through the modulation of NLRP3 inflammasome activity and macrophage infiltration." (PMID 38580672, 2024). "Little is known about the potential effect of mild TBI (mTBI) on the NLRP3 inflammasome and the extent to which modifying factors, such as obesity, may augment the inflammatory response to mTBI." (PMID 38702410, 2024). "In order to further characterise the role of leptin in the modulation of NLRP3 inflammasome profile changes and subsequent macrophage activation in the ovary during obesity, we started by characterising the expression of NLRP3 components in the ovaries of db/db mice." (PMID 38580672, 2024). "Therefore, it is indicated that there is a strong connection between NLRP3 inflammasome and obesity/insulin resistance." (PMID 38317257, 2024). "Therefore, targeting the activation of NLRP3 inflammasome or pyroptosis represents a promising approach for improving obesity." (PMID 38681198, 2024). "Recently, it has been shown that the use of NLRP3 inhibitors in a mouse model of diet-induced obesity could significantly reduce body weight, thus demonstrating the promising potential of targeting NLRP3." (PMID 39275140, 2024). "NLRP3 is the cornerstone of adipose tissue chronic inflammation in obesity and insulin resistance." (PMID 37446154, 2023). "On the contrary, the relative abundance of PCSK9 and NLRP3 positively correlated with obesity diagnosis indices (body weight, fat mass and Lee’s index), abnormal sperm rate, pyroptosis markers including Caspase-1, GSDMD, IL-1, IL-18 and the level of lipid metabolizing hormone (TG, TC and LDL)." (PMID 37935689, 2023). "In fact, the activation of NLRP3 inflammasome in adipose tissues, whether in adipocytes or macrophages, is similar to the development of obesity and leads to production of IL-1β, which participates in the formation and development of IR." (PMID 36993972, 2023). "The NLRP3 inflammasome mediates increased expression of inflammatory markers to promote protein decomposition, while increased IL-1β levels inhibit the mTOR pathway, and increased free fatty acid (FFA) levels caused by obesity inhibit protein synthesis." (PMID 37720530, 2023). "Furthermore, NLRP3 inflammasome suppression has been found to reduce obesity-related inflammation and enhance insulin sensitivity." (PMID 37446154, 2023). "Furthermore, IL-1β is a critical pathological mediator of obesity-induced insulin resistance, and NLRP3 expression depends on NF-κB." (PMID 36902133, 2023). "PPAR-γ has been established to have anti-inflammatory effects by blocking the activation of the NLRP3 inflammasome and the production of its proinflammatory cytokines in diverse inflammatory diseases: cerebral ischemia, spinal cord injury, and obesity." (PMID 37111279, 2023). "However, given the limited number, small sample sizes, and heterogeneity of the reviewed studies, further research is required to elucidate the role of NLRP3 in obesity." (PMID 37446154, 2023). "Gut microbiota dysbiosis may contribute to obesity-associated AF by activating ferritinase and TLR4/NF-κB/NLRP3 inflammasome signaling pathways on atrial pathological remodeling." (PMID 38077349, 2023). "Loss of NLRP3 reverses BAT dysfunction and obesity in PINK1 KO mice." (PMID 37582956, 2023).